IL17RB (interleukin 17 receptor B)
Diseases named in the same sentence as IL17RB in open-access papers (continued):
Sharing a sentence is not in itself a finding about the gene and the disease.
bronchiolitis (1 paper, 2021). Inflammation of the bronchioles characterized by swelling of the bronchioles and mucus accumulation. "In summary, our study found that the specific transcription factors GATA-3, RORα and IL-17RB specifically expressed by the ILC2s in the bronchiolitis group had higher mRNA expression levels than the normal control group." (PMID 33514798, 2021). "Our study found that compared with the control group, the levels of IL-17RB, TSLP, and IL-33 in the bronchiolitis group were significantly increased." (PMID 33514798, 2021). "Therefore, IL-17RB, TSLP, IL-33 may participate in the development of bronchiolitis through ILC2s cells." (PMID 33514798, 2021).
brucellosis (1 paper, 2021). Brucellosis is a bacterial infection that spreads from animals to people via unpasteurized dairy products or by exposure to contaminated animal products or infected animals. "Thus, this work focused on the expression of four Th2 and Th17 immunity-related factors (Th2-LCR lncRNA, IL-25, TRAF3IP2, and IL-17RB) in different stages of brucellosis." (PMID 35071039, 2021). "We investigated the expression of IL-25, IL-17RB, Th2-LCR lncRNA, and TRAF3IP2, which play roles in brucellosis." (PMID 35071039, 2021).
cerebral small vessel disease (1 paper, 2022). Cerebral small vessel disease is the term currently used to pathological processes that affect the brain parenchymal circulation (arterioles, capillaries, and veins). "With a working model suggesting that DIO drives white matter endothelial CXCL5 expression through IL-17B/IL-17Rb signaling, we sought to establish the relevance of this signaling cascade to human cerebral small vessel disease and vascular cognitive impairment." (PMID 36543124, 2022).
colorectal tumor (1 paper, 2024). "In contrast, IL-17RB, a component of the IL-25 receptor, has emerged as a promising candidate because it is expressed on tuft cells and colorectal tumor stem cells." (PMID 37863104, 2024).
dementia (1 paper, 2023). Loss of intellectual abilities interfering with an individual's social and occupational functions. "Our findings highlight the upregulation of several functionally immune-related proteins in dementia, such as IL17D, IL17C, IL17RB, and IL1B, among which IL17D also showed a strong negative correlation with cognitive performance." (PMID 37175824, 2023).
diabetes (1 paper, 2024). "This investigation aimed to ascertain the beneficial regulatory influence exerted by IL-25-induced IL-17RB signal transduction on the recovery mechanism of wounds in individuals with diabetes." (PMID 38802947, 2024). "Interestingly, the expression of IL-17RB is significantly suppressed in the injured skin of diabetic patients suffering from DFUs and in mice with streptozotocin (STZ)-induced diabetes." (PMID 38802947, 2024).
hepatocellular carcinoma (1 paper, 2016). A malignant tumor that arises from hepatocytes. "Studies of hepatocellular carcinoma have shown that IL-17E activates the NFκB and Jak/STAT3 signaling pathways in cancer stem cells, thus resulting in tumor growth and progression and suggesting that IL-17E/IL-17RB may be a therapeutic target in the treatment of this disease." (PMID 27462789, 2016).
myeloid leukemia (1 paper, 2014). A clonal proliferation of myeloid cells and their precursors in the bone marrow, peripheral blood, and spleen. "The IL-17RB locus is a common site of retroviral integration in murine myeloid leukemias, resulting in the upregulation of IL-17RB expression." (PMID 25340344, 2014).
osteoarthritis (1 paper, 2025). A noninflammatory degenerative joint disease occurring chiefly in older persons, characterized by degeneration of the articular cartilage, hypertrophy of bone at the margins and changes in the synovial membrane. "Ultimately, we selected IL-17RB as our target for research to explore whether SGD can mitigate osteoarthritis by alleviating articular cartilage degeneration through the regulation of IL-17RB." (PMID 39964979, 2025).
osteomyelitis (1 paper, 2025). An acute or chronic inflammation of the bone and its structures due to infection with pyogenic bacteria. "We next investigated the clinical significance of PCD pathways by correlating their GSVA scores with representative inflammatory biomarkers of osteomyelitis, including IL6R, MMP8, TNFRSF11A, IL17RB, TNFSF14, and TGFBR1." (PMID 41050653, 2025).
pancreatic ductal adenocarcinoma (1 paper, 2021). An infiltrating adenocarcinoma that arises from the epithelial cells of the pancreas. "To investigate the spatial distribution of IL-17RB expression in pancreatic ductal adenocarcinoma, we determined the expression of IL-17RB and α-SMA in human PDAC samples using immunohistochemistry." (PMID 34771503, 2021).
parasite (1 paper, 2016). "Genes that encode full-length GATA3 and IL17RB were shown to be significantly increased in resistant sheep that had controlled parasite infection." (PMID 27973603, 2016).
parasite infection (1 paper, 2018). "To investigate the role of IL-25R in generation of innate and adaptive type-2 responses following chronic parasite infection, we used mice deficient in the IL-25-specific receptor subunit Il17rb." (PMID 30238872, 2018).
preeclampsia (1 paper, 2025). Preeclampsia is a hypertensive disorder of pregnancy that is characterized by new-onset hypertension with proteinuria presenting after 20 weeks of gestation, and depending on mild or severe forms may initially present with severe headache, visual disturbances, and hyperreflexia. "Although various immune and metabolic pathways have been proposed in late-onset preeclampsia (LO-PE), direct evidence for specific processes—such as Allograft Rejection, Estrogen Response, or Glycolysis—and for genes like HLA-G, IL17RB, and KLRC4 remains limited." (PMID 40427999, 2025).
psoriasis (1 paper, 2021). An autoimmune condition characterized by red, well-delineated plaques with silvery scales that are usually on the extensor surfaces and scalp. "As the major IL-17RB-expressing cells in psoriasis, keratinocytes can be activated by IL-25 via activation of STAT3 transcription factor." (PMID 34122457, 2021). "IL-25 is found to promote proliferation of IL-17RB+ keratinocytes and exacerbation of psoriasis." (PMID 34122457, 2021).
systemic lupus erythematosus (1 paper, 2026). An autoimmune multi-organ disease typically associated with vasculopathy and autoantibody production. "Furthermore, compared with those in the control group, B cells from systemic lupus erythematosus (SLE) patients presented increased levels of fatty acid synthase and decreased levels of IL-17RB." (PMID 40536951, 2026).
tularemia (1 paper, 2021). Tularemia is an infection caused by the bacterium Francisella tularensis. "Il17rb-/- mice were more susceptible to infection with Ft LVS and failed to develop immunity upon secondary challenge suggesting that LPS-specific IgM is one of the protective adaptive immune mechanisms against tularemia." (PMID 34449811, 2021).
vitiligo (1 paper, 2023). Generalized well circumscribed patches of leukoderma that are generally distributed over symmetric body locations and is due to autoimmune destruction of melanocytes. "We noted that other genes, such as Lnc-ARRDC3-1, PLCG1, A_33_P3229958, TERM1, and RAB13, showed increased expression, whereas TM4SF19, IFI27, and IL17RB showed decreased expression in T cells from patients with vitiligo compared with the controls." (PMID 37731844, 2023).
tumor (72 papers, 2010 to 2026). "Previous studies have demonstrated that IL-17RB, a key receptor in the IL-17 signaling pathway, is closely associated with tumor initiation and progression." (PMID 40630198, 2025). "Tumor-derived IL-17B interacting with extracellular bursas causes the expression of IL-17RB in PSCs, reduces mitochondrial fission, increases oxidative phosphorylation, supports pancreatic cancer growth, and accelerates tumor growth in xenograft mouse models." (PMID 37409257, 2023). "We have uncovered a novel association between a higher tumor expression of IL17RB with CD4 Tem, memory B, and activated NK TS and IL17REL with CD8 Tcm, memory B, M1 macrophages and T Helper cell TS and the improved prognosis of HPV-infected HNSCC patients." (PMID 37111458, 2023). "Analysis of secretome transcripts and cognate receptors revealed that tumor expression of IL17RB and IL17REL are associated with a higher viral load and memory B and activated NK cell TS, as well as improved prognosis in HPV-infected HNSCC patients." (PMID 37111458, 2023). "The pro-tumor functions associated with the IL-17B/IL-17RB pathway are diverse and complex because they involve mechanisms that act directly on tumor cells, and also indirect mechanisms that lead to tumor microenvironment remodeling." (PMID 32373132, 2020). "Nevertheless, additional studies with more ATL patient tumor specimens are warranted to further explore the mechanisms underlying IL-17RB overexpression." (PMID 25340344, 2014). "Several reports have shown the association between the IL17B/IL17RB signaling pathway and tumor development in breast, gastric, lung, pancreas, prostate, brain and blood cancers, however the precise mechanisms involved remain unclear." (PMID 37111458, 2023). "In addition to IL-17A, numerous clinical trials have implicated the function of the IL-17B/IL-17 receptor B (IL-17RB) pathway in tumor formation and chemoresistance." (PMID 36313570, 2022). "Tumor-derived IL-17B, carried by extracellular vesicles, activates PSCs and increases the level of IL-17RB." (PMID 40536951, 2026). "The fibroblast-secreted IGFBP-3 subsequently acts on tumor cells to upregulate IL-17RB at the metastatic front in the tumor and promote invasion." (PMID 41226289, 2025). "IL-17RB activates downstream signaling pathways, promoting tumor cell proliferation, invasion, and metastasis." (PMID 40630198, 2025). "There are a number of tumor‐promoting factors in tumor cells such as IL‐17RB, IGF‐1R, MDR1, Bcl‐2, and HMGA2, among others, that can mediate resistance of cancer cells to DOX chemotherapy." (PMID 36684100, 2023). "A recent study has indicated that YTHDF1 is highly expressed in BRCA tumor tissue, creating a “cold” tumor microenvironment by suppressing the release of pro-inflammatory cytokines Ccl7, Il-17rb, Sell, Cxcl2, and Tnfsf4 in BRCA cells." (PMID 38202722, 2023). "The IL‐17B/IL‐17RB pathway is a signaling cascade that can either directly act on the tumor cells or indirectly leads to tumor microenvironment remodeling." (PMID 36325957, 2023). "IL-17RB also plays a unique role in contributing to tumor development and invasion and migration upon stimulation with IL-17B." (PMID 37686343, 2023). "The blockade of IL-33 and/or ST2 results in tumor growth inhibition accompanied by the reduced accumulation of tumor-promoting Treg cells, M2-like macrophages, and IL17RB+ILC2s." (PMID 36291105, 2022). "It has been shown that depletion of IL-17RB in tastuzumab-resistant cell lines ceased colony formation and retarded tumor growth in mice." (PMID 35954312, 2022). "Overexpressing IL-17RB in cancer cell lines resulted in an increased migration in tissue culture experiments and an increased tumor burden in mice after intravenous injection of the cells." (PMID 35883573, 2022). "Compared with control PSCs, tumor size and weight again significantly increased when co-injected with IL-17RB OE PSCs." (PMID 34771503, 2021).
tumor (continued). "We analyze murine as well as human stromal and tumor cells, animal experiments with immunocompromised mice, and human cell lines with overexpression and knockdown of IL-17RB." (PMID 34771503, 2021). "The IL-17B/IL-17RB pathway's protumour functions are different and intricate, owing to the processes that perform unswervingly on tumours apart from unintended mechanisms which force TME reshaping." (PMID 34336101, 2021). "Tumor-derived IL-17B carrying extracellular vesicles (EVs) activated stromal PSCs and induced the expression of IL-17RB." (PMID 34771503, 2021). "IL17RB activates multiple chemokine (such as CCL20/CXCL1/IL8/TFF1) expressions to enhance tumor cell invasion, macrophage, and endothelial cell recruitment at primary sites and cancer cell survival at distant organs." (PMID 34724890, 2021). "Our previous study revealed that the IL-17B/IL-17RB signal promotes the growth and migration of tumor cells, and the expression of IL-17RB is positively correlated with the expression CSC markers." (PMID 33649532, 2021). "In vivo, IL-17RB overexpression in PSCs accelerated tumor growth in a co-injection xenograft mouse model." (PMID 34771503, 2021). "Non‐CSCs secrete IL‐25 into the tumor microenvironment, and secreted IL‐25 interacts with IL‐17RB on CSCs." (PMID 34128588, 2021). "Human PSCs likewise expressed more IL-17RB when co-cultured with human tumor cells compared to naïve PSCs." (PMID 34771503, 2021). "Every study point to the hindrance of the IL-17B/IL-17RB axis through downregulation of receptor expression in tumour cells, utilising diffusing anti-IL-17RB antibodies, reestablished in vitro and in vivo chemosensitivity." (PMID 34336101, 2021). "In the present study, to investigate the effect of IL-17B/IL-17RB signaling on GC cells in vivo, we established a xenograft tumor model through subcutaneous injection of MGC-803 cells treated with rIL-17B or not into nude mice." (PMID 33649532, 2021). "Possibly, HSCs promote liver metastasis via exosome-mediated IL-17B/IL-17RB signaling by increasing oxidative phosphorylation in metastatic tumor cells." (PMID 34771503, 2021). "Altogether, these studies clearly identified IL-17B and IL-17RB as key actors of cell tumorigenesis by enhancing the survival and the proliferative, migratory and invasive properties of tumor cells." (PMID 32373132, 2020). "In vivo studies showed that tumor growth and metastasis formation are reduced in mice xenografted with IL-17RB or IL-17B knockdown cells compared with parental CFPAC-1 and BxPC3 cells." (PMID 32373132, 2020). "In this study, the correlation between IL-17RB expression and poor prognosis was statistically significant even after adjustment for several clinical parameters (age, tumor size, lymph node status and estrogen receptor expression)." (PMID 32373132, 2020). "In vivo, anti-IL-17RB monoclonal antibodies inhibited tumor metastasis and prolonged survival in a mouse xenograft model." (PMID 33244315, 2020). "A positive correlation between tumor growth and the IL‐17RB expression in tumors derived from hBCLN was observed." (PMID 28993429, 2017). "IL-17E, through binding to its own receptor IL-17RB or IL-17RA, shows different properties from IL-17A and IL-17 F in tumor fields." (PMID 27716046, 2016). "CXCL9 was also induced in the metronomic CPA-treated tumor cells in association with other extracellular immune activators: TNFSF4, MICB, interleukins IL12, IL15, IL23, and IL17RB, and interferon response genes." (PMID 25952672, 2015). "Additionally, overexpression of IL-17RB in PSCs promoted tumor development in mice, further validating the role of this signaling pathway in tumor progression." (PMID 40536951, 2026). "HNSCC patients with higher tumor expression of IL17RB combined with high expression of either the CD4 Tem, memory B cell, or aNK TS had improved prognosis compared to patients with lower expression of IL17RB and high expression of either the CD4 Tem, memory B cell, or aNK TS." (PMID 37111458, 2023).
tumor (continued). "Finally, we show that therapeutic use of our vaccine suppresses primary tumor growth and distance metastasis in the syngeneic mouse model through disruption of IL-17RB downstream signaling pathway." (PMID 35214622, 2022). "This difference continued to increase and reached statistical significance (p < 0.05) at the end of the study, which was also shown in the primary tumor weight at the endpoint, suggesting that the IL-17RB specific IgG response suppressed primary tumor outgrowth." (PMID 35214622, 2022). "Our results suggest a pro-tumorigenic effect of stroma-to-tumor IL-17B/IL-17RB signaling and that specific inhibition of the IL-17B receptor could be an effective therapy to suppress the metabolic tumor-stroma cooperation." (PMID 34771503, 2021). "Thus, soluble factors from specific murine and human tumor cell lines stimulate PSCs to upregulate IL-17RB expression." (PMID 34771503, 2021). "Thus, the in vivo results thus further corroborate that IL-17B/IL-17RB signaling strengthens the peritoneal tumorigenesis and invasive abilities of tumor cells." (PMID 33649532, 2021). "Here we show a hitherto unknown metabolic cooperation between pancreatic stellate cells (PSCs) and tumor cells through Interleukin 17B/Interleukin 17B receptor (IL-17B/IL-17RB) signaling." (PMID 34771503, 2021). "The research has implied a crucial role of the IL-17B/IL-17RB signaling cascade in tumor biology." (PMID 33649532, 2021). "IL-17RB OE PSCs are a model for tumor cell-stimulated PSCs in the following experiments." (PMID 34771503, 2021). "We hypothesize that a tumor-promoting interaction of PSCs and tumor cells via IL-17B/IL-17RB may affect energy metabolism." (PMID 34771503, 2021). "However, we identified tumor cell derived extracellular vesicles (EVs) as inducers of increased IL-17RB expression in PSCs that carry IL-17B." (PMID 34771503, 2021). "Thus, we treated the cells with recombinant IL-17B (rIL-17B) to directly stimulate IL-17RB signaling in tumor cells." (PMID 33649532, 2021). "Indirectly co-cultured murine PSCs with murine tumor cells expressed more IL-17RB than naïve PSCs." (PMID 34771503, 2021). "In addition to blood components, IL‐25 and IL‐25R (IL‐17RB) expression have also been examined in different types of cancer cell lines and tumor tissues." (PMID 34128588, 2021). "Our study demonstrates the tumor-promoting effect of PSCs via IL-17B/IL-17RB signaling." (PMID 34771503, 2021). "CM of IL-17RB KD PSCs tended to decrease the OCR in Panc-1 tumor cells compared with control PSCs." (PMID 34771503, 2021). "IL-17RB OE PSCs again significantly accelerated tumor growth compared with control PSCs." (PMID 34771503, 2021). "Importantly, in each study, inhibition of the IL-17B/IL-17RB axis by downregulating receptor expression in tumor cells or by using neutralizing anti-IL-17RB antibodies restored chemosensitivity in vitro and in vivo." (PMID 32373132, 2020). "This also suggests that stimulation by any other IL-17RB-positive cells from the tumor microenvironment might indirectly contribute to the tumor progression." (PMID 32373132, 2020). "Both tumor growth and lung nodules were reduced in Il‐17rb‐knockout 4T1 cells." (PMID 28993429, 2017). "Thus, it is likely that tumor cells induced Bregs to expand Tregs for at least two potential functions, one is to inactivate NK cells and the other is to up‐regulate IL17RB in cancer cells." (PMID 28993429, 2017). "Collectively, our data demonstrate that the IL-17E/IL-17RB pathway contributes to TNBC resistance to EGFR therapeutics through a loop that amplifies and sustains the phosphorylation of the main EGFR downstream kinases implicated in tumor resistance." (PMID 27462789, 2016). "In our TNBC model, direct IL-17E signaling via IL-17RB activated various signaling pathways associated with IL-17-induced tumor proliferation and progression and did not induce tumor cell apoptosis." (PMID 27462789, 2016).